ASH2L (ASH2 like, histone lysine methyltransferase complex subunit)
Diseases named in the same sentence as ASH2L in open-access papers (continued):
Sharing a sentence is not in itself a finding about the gene and the disease.
renal fibrosis (1 paper, 2022). A final common manifestation of a wide variety of chronic kidney diseases characterized by glomerulosclerosis and tubulointerstitial fibrosis. "As HIPK2 has been identified as a key regulator of renal fibrosis, we determined whether ASH2L affects HIPK2 expression." (PMID 36553510, 2022). "ASH2L could activate the transcription of HIPK2 (a key regulator of renal fibrosis) and increase its protein expression through H3K4me3 in the HIPK2 promoter region, thereby mediating renal fibrosis and inflammation in DN." (PMID 36553510, 2022).
tumor (17 papers, 2018 to 2026). "In the end, we found that high circ-ASH2L expression is related to tumor progression and is an independent risk factor for PDAC patient survival." (PMID 31718694, 2019). "By conducting gain-of-function or loss-of-function circ-ASH2L and miR-34a experiments, we found that circ-ASH2L promotes tumor progression via miR-34a." (PMID 31718694, 2019). "ASH2L directly influences the regulation of cell cycle genes and promotes tumor cell survival both in vitro and in vivo." (PMID 40565099, 2025). "Inhibiting additional members of the menin–MLL complex, MLL1 and Ash2L, similarly reduced tumor organoid growth and HIF target gene expression, suggesting the menin–MLL complex functions as a tumor promoter in endometrial cancer." (PMID 39336822, 2024). "Here, we show that ASH2L directly regulates cell cycle-related genes and facilitates tumor cell survival both in vitro and in vivo." (PMID 37974198, 2023). "Similar to circNFIX, circ-ASH2L functions as a miRNA sponge for miR-34a and promotes tumour progression in vivo." (PMID 37628760, 2023). "Lastly, we checked if there was any evidence of tumor samples that showed decreased levels of ASH2L gene expression." (PMID 33257682, 2020). "ASH2L has been shown to be overexpressed at the protein level in most human tumors and tumor cell lines, and its knockdown inhibited the proliferation of tumor cell lines." (PMID 33302406, 2020). "We identified a circRNA (circ-ASH2L) based on our previous studies, detected its expression in different malignant cells and found that circ-ASH2L was highly expressed in pancreatic cells or tumor tissues and correlated with tumor malignancy." (PMID 31718694, 2019). "Our in vivo assay showed that circ-ASH2L promoted tumorigenesis and tumor progression, and further correlation analysis in clinical PDAC samples showed that high circ-ASH2L was associated with lymphatic invasion or TNM stage." (PMID 31718694, 2019). "The results above suggest that circ-ASH2L was correlated with tumor malignancy; thus, we investigated the specific cellular functions of circ-ASH2L in PDAC cells." (PMID 31718694, 2019). "By serving as a ceRNA for miR-34a, circ-ASH2L promoted tumor invasion, proliferation and angiogenesis by regulating miR-34a expression to active Notch 1 pathway." (PMID 31718694, 2019). "We first detected circ-ASH2L in 25 pairs of PDAC tumor tissues and their adjacent normal tissues, qRT-PCR analysis indicated that circ-ASH2L transcripts were highly expressed in PDAC tumors compared with adjacent normal tissues." (PMID 31718694, 2019). "Further studies revealed that circ-ASH2L promoted tumor invasion, proliferation and angiogenesis by regulating miR-34a, thus regulate Notch 1 expression." (PMID 31718694, 2019). "It remains unclear whether lactylation modification of ASH2L correlates with the HCC tumor phenotype, and further investigation is warranted." (PMID 40726441, 2025). "Interestingly, knocking down MLL and the menin–MLL complex member ASH2L behaves similarly to menin knockdown in reducing AR-target gene expression, cell proliferation, and tumor growth." (PMID 39336822, 2024). "Meanwhile, ASH2L overexpression can also significantly contribute to tumor proliferation." (PMID 38115111, 2023). "Interestingly, some TC tumor samples presented very low levels of ASH2L mRNA, even below the levels detected in normal tissues." (PMID 33257682, 2020). "The results above suggest that circ-ASH2L plays important roles in tumor progression in vitro." (PMID 31718694, 2019). "circ-ASH2L play an important role in tumor invasion, and high circ-ASH2L may be a useful marker of PDAC diagnosis or progression." (PMID 31718694, 2019). "Together, the results above suggest that circ-ASH2L promotes tumor progression via miR-34a." (PMID 31718694, 2019).
tumor (continued). "As the cellular functions of circ-ASH2L and miR-34a are quite similar, and we demonstrated that circ-ASH2L acts as a sponge for miR-34a, we investigated whether circ-ASH2L promotes tumor progression via miR-34a." (PMID 31718694, 2019). "Circ-ASH2L served as a miRNA sponge for miR-34a and promoted tumor progression in vivo." (PMID 31718694, 2019). "Finally, we analyzed circ-ASH2L expression in clinical tumor samples and showed that circ-ASH2L may have important functions in PDAC." (PMID 31718694, 2019). "The results above suggest that circ-ASH2L could promote tumor progression in vivo." (PMID 31718694, 2019). "ASH2L-mediated tamoxifen resistance and CSC activity were evaluated through in vitro assays, including SRB, colony formation, tumour sphere formation, and FACS, and in vivo xenograft models." (PMID 41735581, 2026). "Circ-ASH2L-mediated activation of NOTCH signaling pathway promotes angiogenesis, tumor growth, and tumor invasion." (PMID 34591242, 2021). "Because PDTC reduced in vivo tumor growth in nude mice, we examined the expression of ZNF479, MT-1, ASH2L, Menin, DNMT1, and UHRF1 in PDTC-treated tumors from mice." (PMID 31138789, 2019). "At present, Ash2l and its mediated H3K4 methylation are mainly reported in tumor-related research." (PMID 38280036, 2024). "In support of a potential role of ASH2L in tumor formation, ASH2L protein but not mRNA is overexpressed in the large majority of human tumors of different origin." (PMID 29498679, 2018). "However, we also found that a circ-RNA, circ-ASH2L, was abundant only in tumor cells, rather than in tumor exosomes." (PMID 31718694, 2019).
cancer (14 papers, 2009 to 2025). A tumor composed of atypical neoplastic, often pleomorphic cells that invade other tissues. "Prompted by the remarkable overlap in ASH2L and CHD1 target genes, we examined their loss-of-function in diverse cancer types and found mutations in CHD1 and histone lysine methyltransferases of the MLL complexes frequently co-occurred." (PMID 41168190, 2025). "A comparable AlphaScreen signal was observed for MLL1 wild‐type and all cancer variants, which is indicative of a similar interaction of all MLL1 proteins with the RBBP5/ASH2L heterodimer." (PMID 28182322, 2017). "BMX, BMPR1B, BTK, and MDC1 belong to the COSMIC_mut gene set, and CSNK2A2 belongs to the COSMIC_other gene set, while ASH2L belongs to the non-cancer gene set." (PMID 19765316, 2009). "Along with epigenetic modifiers that were previously implicated in cancer cell fitness, such as CHD1, CHD4, DNMT3B, ELP3, SUPT16H, SUV39H2; novel hits ASH2L, RBX1 and SSRP1 were discovered as essential genes for both U373 and T98G cells suggesting common regulatory role." (PMID 37974198, 2023). "Therefore, high throughput, robust and affordable screens with focused libraries, such as EpiDoKOL, holds great promise to enable rapid discovery of novel epigenetic regulators of cancer cell survival, such as ASH2L." (PMID 37974198, 2023). "Within the context of personalized cancer therapy, decreased ASH2L levels could be used as a biomarker for predicting a poor response to DNA damaging agent-based therapy." (PMID 33257682, 2020). "Interestingly, this patient presenting amplification of the ASH2L gene (patient ID: TCGA-2G-AAF6), also presented a KRAS G12V mutation, a mutation that is well-known to negatively impact overall cancer survival and relapse." (PMID 33257682, 2020). "Although ASH2L was originally included in the "non-cancer" gene set, a positive prediction from our cancer gene classifier and observed phenotypes from siRNA experiments indicate that ASH2L might be a novel cancer gene." (PMID 19765316, 2009). "For such cancers, ASH2L levels could be used as a biomarker to predict the response to genotoxins." (PMID 33257682, 2020). "Best predicted cancer immunotherapy proteins with BC were RPS27, SUPT4H1, CLPSL2, POLR2K and RPL38, and the most altered ones were POLR2K, ASH2L, MED30, NSL1 and RPRD2." (PMID 32444848, 2020). "Here we show that HL and TC cancer cells depleted of ASH2L (Absent, Small, or Homeotic-Like 2) are more resistant to bleomycin and other DNA damaging agents." (PMID 33257682, 2020). "Notably, we identified ASH2L as a common essential gene in both cancer types through EPIKOL screens, but it was not classified as a common essential gene in previously performed screens." (PMID 35973998, 2022).
ASH2L also shares sentences with these, for which no sentence is quoted: hepatocellular carcinoma (2 papers); infection (2); leukemia (2); lung carcinoma (2); colon adenocarcinoma (1); fibrosis (1); glioma (1); heart defects (1); Hyperglycemia (1); inflammation (1); Kawasaki disease (1); myelogenous leukemia (1); ovarian carcinoma (1).